CD3E (CD3 epsilon subunit of T-cell receptor complex)
Diseases named in the same sentence as CD3E in open-access papers (continued):
Sharing a sentence is not in itself a finding about the gene and the disease.
glioma (9 papers, 2010 to 2025). A benign or malignant brain and spinal cord tumor that arises from glial cells (astrocytes, oligodendrocytes, ependymal cells). "Studies have shown that combining CD3E antibodies with antibodies that bind to mutant epidermal growth factor receptor variant III can effectively treat mice with gliomas." (PMID 34557404, 2021). "Recent studies have identified ITPRIPL1, a newly reported CD3ε‐inhibitory ligand, as a suppressor of T cell activation, thereby facilitating tumor immune evasion and offering a novel avenue for immunotherapeutic intervention in glioma." (PMID 40792394, 2025). "Still, it is an interesting question that CD3E may have a completely opposite prognostic effect in gliomas than that in most other tumors." (PMID 34557404, 2021). "After a literature review and pan-cancer statistical tests, we found that CD3E may have a completely opposite prognostic effect in gliomas than in most other tumors, except for Uveal Melanoma and LGG." (PMID 34557404, 2021). "Furthermore, CD3E was positively related to glioma and immune cell response." (PMID 34557404, 2021). "Therefore, we speculate that CD3E and miRNAs may affect the invasion of glioma through the ion glutamate synapse." (PMID 34557404, 2021). "Interestingly, after a literature review and pan-cancer statistical tests, we found that CD3E may have an opposite prognostic effect in gliomas than in most other tumors." (PMID 34557404, 2021). "Studies have reported that CD3E affects the TME and the prognosis of patients with cancer, including those with low-grade glioma, cervical squamous carcinoma, head and neck squamous cell carcinoma, and bladder cancer." (PMID 37031292, 2023). "Therefore, we studied the expression of CD3E in pan-cancer cell lines, and we found that the expression of CD3E in all tumors is not the highest in gliomas." (PMID 34557404, 2021). "Next, we enrolled six glioma single-cell sequencing datasets from GEO analysis (GSE131928 10X, GSE131928 Smartseq2, GSE135437, GSE139448, GSE141982, and GSE148842), which suggested significantly elevated CD3E expression in CD8+ T cells, especially the exhaustive T cells." (PMID 34557404, 2021). "Finally, although mRNA for the T cell-specific complex, CD3ε, is not detectable in normal or Rag1−/−-glioma mouse brain, it is induced in WT-glioma mouse brain (7367±2570%)." (PMID 21060663, 2010). "However, IL-17A expression appears to be dependent on T cell accumulation, since IL-17A mRNA levels were not different between types of human glioma, when normalized to CD3ε mRNA levels." (PMID 21060663, 2010). "However, malignant behavior of CD3E in progression of glioma cell was not elucidated in this study." (PMID 34557404, 2021).
bladder cancer (8 papers, 2020 to 2024). "A bioinformatics analysis using TCGA data from bladder cancer patients found CD3E to be downregulated in the luminal compared to basal tumor samples, with the luminal subtype being associated with better survival rates." (PMID 36291815, 2022). "CD3e was found to potentially serve as an indicator of tumor microenvironment (TME) regulation in bladder cancer, and the therapies targeting CD3e can be novel therapeutic strategies." (PMID 35184642, 2022). "Immunohistochemical staining showed a consistent expression trend of LCK and CD3E between normal tissue and bladder cancer samples." (PMID 35004669, 2021). "Moreover, FN1, CXCL12, CD3E, LCK, and ZAP70 were key interconnected node genes in PPI networks and are also associated with overall survival in patients with bladder cancer." (PMID 33204728, 2020). "Interestingly, regulatory T cells are related to CD3E in bladder cancer." (PMID 38564630, 2024). "Two bladder cancer cohorts (GSE176307 and IMvigor210) receiving immunotherapy were recruited to validate the prognostic value of LCK and CD3E for immunotherapy." (PMID 35004669, 2021). "As an indicator of bladder cancer TME regulation, CD3E is closely related to immune infiltration." (PMID 34490269, 2021).
leukemia (8 papers, 2008 to 2025). A malignant (clonal) hematologic disorder, involving hematopoietic stem cells and characterized by the presence of primitive or atypical myeloid or lymphoid cells in the bone marrow and the blood. "In mouse leukemias, Cdkn1a expression was decreased in pre-LSCs compared to wild-type DN3a thymocytes and was further reduced in leukemic cells, in both Cd3e+/+ and Cd3e-/- leukemias." (PMID 35401501, 2022). "We characterized the leukemia type using major lineage markers, including Mac1, B220, and CD3e, to delineate myeloid, B-cells and T-cells, respectively." (PMID 33602907, 2021). "In mice with leukemia, the size of the myeloid compartment in the PB, based on CD11b+ population, was also expanded in the PB in comparison to B220+CD3e+ lymphoid population." (PMID 33957868, 2021). "The latency of the disease was not significantly different between E2A-PBX1/CD3ε−/− and HOXB4/E2A-PBX1/CD3ε−/− mice, but the authors detected a higher number of leukaemia-initiating cells upon HOXB4 expression." (PMID 28819864, 2018). "Four of these genes were reported for leukemias (IRS1, RUNX2, CCDC50 and ROBO3) and four others were reported to be involved in other types of cancers (NSG1, CAMK1D, CD3E, KLF8)." (PMID 41146244, 2025). "We performed exome sequencing of Cd3e-/-SCLtgLMO1tg leukemias (n=4) and control Cd3e-/thymocytes to identify genetic alterations involved in leukemia development in the absence of pre-TCR signaling." (PMID 35401501, 2022). "Using Cd3e-/- mice in which pre-TCR function is abrogated, we now show that oncogenic Notch1 controls disease penetrance in SCL-LMO1-induced T-ALL while the pre-TCR signal governs the time of leukemia onset." (PMID 35401501, 2022). "All the MYC/HOXA9- and HOXA9/MEIS1-induced leukemias were positive to a myeloid marker Mac1 but negative to lymphoid marker B220 or CD3e, indicating that both MYC/HOXA9- and HOXA9/MEIS1-combinations induced myeloid leukemia." (PMID 34310280, 2021). "In line with our work, it has recently been described that T-ALL and leukemia stem cells highly express the oxysterol-binding protein (OSBP)-related protein 4 ORP4L, which acts as an adaptor/scaffold assembling CD3ε, Gαq/11, and PLCβ3 into a complex that activates PLCβ3." (PMID 33440859, 2021). "In addition, Nfkb1-deficient leukemic cells presented a cell surface marker phenotype (expression of variable levels of CD4, CD8, CD24, CD25, and TCRβ/CD3ε) similar to that of Nfkb1-proficient cells (data not shown) and characteristic of transgenic TEL-JAK2 leukemia." (PMID 18596915, 2008).
T-cell lymphomas (7 papers, 2020 to 2026). "The initial detection of cytoplasmic CD3ε, together with the angiocentric and angiodestructive features of the tumour, resulted in its classification as an angiocentric T-cell lymphoma." (PMID 35158865, 2022). "We first observed that CD3ε+ cells were capable of developing in these SCID pigs when two ART16/16 bone marrow transplanted pigs developed host-derived T cell lymphoma." (PMID 32296428, 2020). "Among the SCID pigs that underwent BMT, two ART16/16 pigs developed host derived CD3ε+ T-cell lymphoma." (PMID 32296428, 2020). "Similarly to CD5 and CD7 molecules, CD3 was firstly evaluated as a therapeutic target in patients with T-cell lymphoma in studies using immunotoxin-loaded anti-CD3ε mAbs." (PMID 33081391, 2020). "CD3 is a multimeric (CD3ε, CD3γ, CD3δ, CD3ζ) protein complex widely expressed at variable intensity levels on the cell surface of mature T-cell lymphomas and mature T-ALLs, whereas cytoplasmic CD3 expression is a mandatory diagnostic marker for immature T-ALL subtypes." (PMID 33081391, 2020). "A strategy to target TCRαβ on T cell lymphomas is in trial and relies on discriminatory targeting of TRBC1 or TRBC2, but would not be suitable to combine with CD3ε given their linked multimeric expression." (PMID 34035409, 2021). "Typical NK/T-cell lymphomas are characterized by a specific T-immunophenotype with immunohistochemical features that include positive staining for CD2, CD56, and cytoplasmic CD3ε, whereas surface CD3 is usually negative." (PMID 40438688, 2025).
colitis (6 papers, 2014 to 2021). Inflammation of the colon. "The anti-mouse CD81 antibody also had no influence on the cytokine production of splenocytes from mice with TNBS-induced colitis, which were stimulated with the immobilised anti-mouse CD3ε antibody or SEB." (PMID 32332834, 2020). "The CD3e+CD4+CD25+FOXP3+ Tregs were significantly induced in the MLN cells from the mice with DSS-induced colitis followed with T. spiralis AES treatment compared to the DSS-induced mice (P<0.05)." (PMID 24788117, 2014). "We noted that the percentages of CD3e+CD4+CD25+Foxp3+ cells in the spleens of mice with DSS-induced colitis that were treated with M2b macrophage exosomes were significantly increased (12.7 ± 0.7%; P < 0.05), compared with those in the spleens of PBS-treated mice with DSS-induced colitis (9.3 ± 1%)." (PMID 31749791, 2019). "The reduced number of IEL CD3ε+ T cells in prolapse-free CD4cre:PP4f/f mice and their normal cytokine productions thus suggest that the ablation of PP4 does not induce the accumulation of pro-inflammatory T cells in the gut to cause colitis onset." (PMID 24904742, 2014). "In addition, the percentages of CD3e+CD4+CD25+Foxp3+ cells in the spleens of mice with DSS-induced colitis that were treated with M2c macrophage exosomes were significantly increased (13.5 ± 3%; P < 0.001) compared with PBS-treated mice with DSS-induced colitis (9.3 ± 1%)." (PMID 31749791, 2019). "Intracellular cytokine staining of colonic CD3ε+ T cell subsets demonstrated a significant increase in the frequency and absolute cell count of both IL-17A+ γδ and αβ CD4+ T cell subsets in the recovery phase of aDSS colitis." (PMID 30876876, 2019).
head and neck squamous cell carcinoma (6 papers, 2016 to 2025). A squamous cell carcinoma that arises from any of the following anatomic sites: lip and oral cavity, nasal cavity, paranasal sinuses, pharynx, larynx, and salivary glands. "Previous study has revealed that patients with head and neck squamous cell carcinoma (HNSCC) with low CD3E expression have a poor prognosis." (PMID 34218795, 2021).
lung carcinoma (6 papers, 2015 to 2024). "Previous studies have shown that CD3D may serve as a prognostic maker of colon cancer, gastric cancer and other tumors; CD3E can be used as a prognostic factor of lung cancer; the expression of CD247 was associated with many cancers, including gastric cancer, head and neck cancer and ovarian cancer." (PMID 36176400, 2022). "For spatial analysis, the first two TAIC subtypes closest to malignant cells were F4-80+ macrophages and CD3e+ T cells, which is similar to our previous finding in human lung cancer, suggesting these two subtypes played essential roles in lung cancer." (PMID 38877529, 2024). "Densities of CD3e+ T cells (total T cells) were also much lower in this cohort than in human lung cancer." (PMID 38877529, 2024). "In human lung cancer, the density of CD3e+ T cells was the highest among all TAICs, and CD3e+ T cells in mice lung cancer had much lower density than in human lung cancer." (PMID 38877529, 2024). "LCK, one of the core of LUAD pivotal genes, is an independent predictor of recurrence-free and overall survival in lung cancer patients, which can coordinate the tumor microenvironment with CD3E to promote immunotherapy response and survival in patients with muscle-invasive bladder cancer." (PMID 36744181, 2022). "Additionally, in the two lung-carcinoma samples where tumor parenchyma and brain tissue were visible, CD3E transcript levels were highest at the tumor interface with brain." (PMID 35584630, 2022). "It is possible that the down-regulation of CD3-ε in patients with lung cancer may be related to TCF7 dysfunction through the regulation of TCF7 in CD3E expression." (PMID 26289446, 2015). "Previous studies showed that NSCLC cells could induce the down-regulation of CD3-ε in Jurkat T cells which might be responsible for T-cell anergy in lung cancer." (PMID 26289446, 2015). "For instance, downregulation of CD3ε but not CD3ζ expression in CD4+ and CD8+ T cells has been reported in patient with lung carcinomas." (PMID 29951063, 2018).
ovarian carcinoma (6 papers, 2021 to 2025). A malignant neoplasm originating from the surface ovarian epithelium. "We used two tumor xenograft mouse models to evaluate the in vivo anti‐tumor activity of CD3ε FP T cells: a tumor model based on the ovarian cancer OVCAR‐3 cell line, and a tumor model based on the rapidly growing B cell lymphoma Raji cell line." (PMID 38023726, 2023). "All CD3ε FP T cells displayed anti‐tumor activity relevant to the specific tumor target, however TAG‐72/CD3 FP T cells could not suppress tumor growth for as long as the lentiviral transduced TAG‐72 CAR‐T cells in the established ovarian cancer cell tumor model." (PMID 38023726, 2023).
colon carcinoma (5 papers, 2016 to 2025). "IP expression also correlated with the expression of CD3E, CD8 and PRF1 in colon cancer, another form of solid tumor infiltrated by TILs21 (data not shown)." (PMID 27659694, 2016).
lung adenocarcinoma (5 papers, 2019 to 2025). A carcinoma that arises from the lung and is characterized by the presence of malignant glandular epithelial cells. "An automated eight-color mIF panel was evaluated to study the TME using seven antibodies, including cytokeratin 19, CD3e, CD8a, CD4, PD-1, PD-L1, F4-80 and DAPI, then was applied in six mice lung adenocarcinoma samples." (PMID 38877529, 2024). "Lastly, although the authors observed inverse correlations between EPHA2 and CTL gene signatures in human pancreatic cancer, we did not discover any consistent trends between EPHA2 and CD3E, CD8B, GZMA, GZMB, PRF1, or IFNG expression from the TCGA lung adenocarcinoma dataset." (PMID 40867322, 2025).
squamous cervical cancer (5 papers, 2015 to 2021). "Similar result was also observed in squamous cervical cancer that high expression of CD3E tends to have better prognosis." (PMID 33747959, 2021). "Consistently, among these, a previous study using squamous cell cervical cancer samples demonstrated that the high expression of the T cell receptor component, CD3E, is correlated with improved patient survival." (PMID 30445744, 2018). "By using a qRT-PCR array, we identified CD3E, IL6, VEGFA and a high IL6/IL17 ratio combined with low IL5 expression as the most prognostic factors in squamous cervical cancer." (PMID 25889974, 2015).
Stroke (5 papers, 2014 to 2022). Sudden impairment of blood flow to a part of the brain due to occlusion or rupture of an artery to the brain. "The upregulation of Cd3d, Cd3e, Cd3g, Blnk, Sdc1, and Jchain suggests that chronic inflammation persists in peri-infarct regions for at least 7 weeks after stroke." (PMID 34819339, 2022). "To determine if T-lymphocytes follow a similar infiltration pattern, we also stained the naïve mice, as well as the mice sacrificed at 24 hours, 1 week, 2 weeks, 4 weeks, and 7 weeks following stroke for CD3ε." (PMID 32956832, 2021). "Fold change difference in the expression of B2M and CD3E in late phase stroke versus control subjects." (PMID 25090612, 2014). "By all methods B2M expression was significantly increased in whole blood in the delayed phase of stroke and CD3E was significantly increased in CD4 cells." (PMID 25090612, 2014). "We first identified CD3ε+ T cells in the peripheral blood of controls and stroke patients." (PMID 33205448, 2021). "Immunostaining revealed a substantial reduction in CD3e+ T-lymphocyte, B220+ B-lymphocyte, and CD68+ macrophage/microglia infiltration at 24 weeks following stroke compared to eight weeks following stroke, and trichrome staining demonstrated a concurrent increase in collagen scarring." (PMID 30417081, 2018).
cervical carcinoma (4 papers, 2015 to 2023). A carcinoma arising from either the exocervical squamous epithelium or the endocervical glandular epithelium. "In cervical carcinoma, low expression of CD3E was correlated with poor disease-specific and disease-free survival, and high CD3E expression was correlated with improved disease-specific survival." (PMID 34054929, 2021). "Remarkably, high CD19 expression was significantly correlated with improved disease-free survival (based on fresh-frozen tumor tissue samples obtained from an additional cervical cancer patient cohort), whereas CD3E, CD20 and TCL1A were not significantly correlated with survival." (PMID 26299617, 2015).
Granuloma (4 papers, 2015 to 2020). A compact, organized collection of mature mononuclear phagocytes, which may be but is not necessarily accompanied by accessory features such as necrosis. "We further compared liver pathology between wild-type and CD3e−/− B6 mice by analyzing granuloma and fibrosis using H&E staining and Masson’s trichrome staining, as well as fibrosis related marker genes expression." (PMID 33347431, 2020). "We observed that granulomas showed co-expression of Inos and different T-cell-related transcripts (Cd3e, Tcrb, Cd8b) at 3 wpi." (PMID 31015452, 2019). "Furthermore, CD3ε−/− mice presented an active pneumopathy with large granulomas and hemorrhagic foci at day 22, while TCRα−/− lung histology was close to normal with only a slight increase of inflammatory cells in the inter-alveolar septa." (PMID 25747674, 2015). "The density of several transcripts including Ccr6, Cd19, and Il12, and to a lesser degree Cd3e, Cxcr3, and Cd8b mRNA was increased in the lymphoid in relation to the epithelioid areas after a supervised annotation of the lymphoid and the epithelioid areas of the granulomas based on H&E staining." (PMID 31015452, 2019).
viral infection (4 papers, 2013 to 2022). "NKT cells of the peripheral blood in C. carbonaria were identified by PITPNM2, OGT, PRPF4B, PNISR, and CD3E genes, which had immunoregulatory roles in virus infection and cancer." (PMID 36552787, 2022). "Whereas, the CD3E+CD8A+CD4− clusters contributed substantially to all of top 20 TCR data in three groups’ integrated data, which indicated expanded CD8+ T cell clones contributing to immune response to viral infection." (PMID 34580278, 2021).
acute lymphoblastic leukemia (3 papers, 2021 to 2026). Leukemia with an acute onset, characterized by the presence of lymphoblasts in the bone marrow and the peripheral blood. "Blinatumomab, a bispecific T cell engager (BiTE) antibody targeting CD19 and CD3ε, can redirect T cells toward CD19-positive tumor cells and has been approved to treat relapsed/refractory B-cell acute lymphoblastic leukemia (R/R B-ALL)." (PMID 34117317, 2021).
acute T-cell leukemia (3 papers, 2020 to 2026). "It has been established that CD3E is overexpressed in patients with T-cell ALL, and that patients with this condition and that a remission of the disease can be obtained with an anti-CD3E recombinant immunotoxin." (PMID 33195511, 2020). "Potentially, blv-miR-B1-5p has a role in the overexpression of CD3E in T-cell ALL patients; however, further studies would be needed to establish this effect." (PMID 33195511, 2020). "Only limited binding of DuoBody-CD3x5T4 to human CD3ε expressed on Jurkat (acute T-cell leukemia) cells could be detected by flow cytometry, in line with the relatively low affinity for CD3ε." (PMID 36271507, 2022).